IGF1R (insulin like growth factor 1 receptor)
Diseases named in the same sentence as IGF1R in open-access papers (continued):
Sharing a sentence is not in itself a finding about the gene and the disease.
tumor (continued). "This raises the question as to whether the presence of nuclear IGF-1R indicates strong IGF axis activation, perhaps to the point where the tumor is dependent on IGF signaling." (PMID 27200287, 2016). "Analysis of tumor from the 2015 (post-trial) recurrence showed that EGFR and IGF-1R were still detectable, but with reduced intensity compared with the 2008 recurrence, and reduced nuclear IGF-1R." (PMID 27200287, 2016). "Finally, in vivo experiments show AE attenuated the growth of the xenograft and expression of IGF1R and SNAIL1 while increasing the expression of E-cadherin in the tumor." (PMID 27129171, 2016). "Moreover, several studies have reported IGF1R expression in ESFT and OS tumor samples and IGF1R signaling dependency in cell cultures." (PMID 27374103, 2016). "Hence, we compared tumor growth rate following inoculation of CD24- control and CD24- IGF1R-KD cells and following inoculation of CD24+ control and CD24+ IGF1R-KD cells into the mammary fat pad of WT and MKR female mice." (PMID 27179633, 2016). "More importantly, knocking down of IGF1R reduced tumor-propagating capacity of CEA−/lo CRC cells without affecting tumorigenic ability of CEA+ CRC cells." (PMID 27813496, 2016). "Finally, AE significantly decreased the expression of IGF1R and SNAIL1 proteins during attenuation of SKOV3-derived xenograft tumor." (PMID 27129171, 2016). "The tumor volume in the tumor-bearing mice inoculated intratumorally with lentivirus-IGF-1R siRNA was markedly smaller compared with the negative control group or blank control group mice (n = 4/group)." (PMID 27813495, 2016). "For example, interactions between the EGFR, IGF-1R and VEGFR signaling pathways are well established and target inhibition within one system commonly impacts molecular signaling (and ultimately tumor response) via compensatory response from companion RTK pathways." (PMID 27716204, 2016). "Western immunoblotting showed that MGCD516 treatment not only resulted in significant blockade of phosphorylation of multiple RTKs such as PDGFR, c-Kit and IGF1-R but also inhibited downstream effectors such as p-AKT and p-S6 which are critical for tumor cell survival and proliferation." (PMID 26675259, 2016). "In contrast, the primary tumours were either completely negative (66 %) or showed very weak staining (34 %) for IGF1R." (PMID 27418340, 2016). "Though tumor samples exhibited a broad range of cell-surface expression of EGFR, c-Met, and IGF-1R, no cell-surface erythropoietin receptor was detected in tumor cells from the 186 tumors examined (by flow cytometry or Western blot)." (PMID 25807104, 2015). "Likewise, IGFs/IGF-1R signaling is highly active in CRC, contributing to the activation of multiple pathways that increase the aggressiveness of the tumor phenotype." (PMID 26528439, 2015). "Tumor cells have been shown to develop alternative compensatory pathways to sustain cell proliferation, ultimately leading to drug resistance, such as HER3, IGF-1R, EGFR and insulin receptor pathways." (PMID 25762617, 2015). "The present findings show for the first time that crizotinib may also act on IGF1R activity, thus circumventing possible resistance mechanisms driven by IGF1R signalling observed in RMS tumours." (PMID 26445453, 2015). "Furthermore, both IGF-1R and VEGFR-2 were found in a liquid biopsy assay to be co-expressed in circulating tumor cells (CTCs)." (PMID 25743390, 2015). "The IGF1/IGF1R axis is overexpressed and constitutively phosphorylated especially in PAX3/7-FOXO1 positive ARMS cells, this being one of the major tumorigenic pathways in this tumour." (PMID 26445453, 2015). "Here we assessed whether the combination of two therapeutic monoclonal antibodies, cetuximab, and IMC-A12 that specifically target EGFR and IGF-1R, respectively, would enhance HNSCC tumor response to radiation." (PMID 25355701, 2015).
tumor (continued). "IGF-1R does not solely drive tumour cell proliferation; however, most oncogenes are required in mediating anchorage independent growth given its property to mediate proliferation and cell survival." (PMID 25866791, 2015). "This study is the first to describe the in vitro activity of crizotinib in RMS tumours, this suggesting that this molecule may be a potential therapeutic agent that effectively controls ARMS growth by inhibiting ALK, MET and IGF1R pathways." (PMID 26445453, 2015). "Our findings support the clinical studies that demonstrated tumor responsiveness to IGF1R antibody in patients whose tumors did not express IGF1R." (PMID 25170759, 2014). "An animal tumor model was established by subcutaneously injecting TE-1 or Eca-109 cells to test the anti-tumor effects of radiation therapy in vivo in the presence or absence of IGF-1r siRNA." (PMID 25363593, 2014). "GALNT2 can modify IGF-1R O-glycosylation and interfere with IGF-1-triggered dimerization and activity of IGF-1R, thereby regulating downstream signaling events related to malignant properties of NB cells in vitro and tumor growth in vivo." (PMID 25362349, 2014). "In the attempt to confirm whether the effects of IGF-1R and IRS-2-mediated let-7b on proliferation observed in OSCC cells and clinical specimens were related to tumor growth." (PMID 24810113, 2014). "In HCC, IGF1R expression seems not to be correlated with tumour size, histological differentiation, capsular invasion and portal venous invasion." (PMID 25225571, 2014). "In vivo and in vitro studies using IGF-1R antibodies, small molecule inhibitors, and antisense technology have shown that IGF-1R is functionally essential for tumor cell growth and proliferation in most if not all forms of cancer." (PMID 24276851, 2014). "Summarizing the previously reported data, M31 did not demonstrate tumor inhibition to any of the anti-IGF1R antibodies." (PMID 25170759, 2014). "Additional sequence alterations were present in the OS primary tumor samples, but these did not correlate with differences in response to treatment with anti-IGF1R antibody in the xenograft models." (PMID 25170759, 2014). "Compared to the combination therapy group, larger tumor sizes and lower survival rates were obtained after radiation therapy in the absence of IGF-1r siRNA treatment." (PMID 25363593, 2014). "We next examined whether the relative expression of IGF1R and IR receptors affected the ability of IR47-9 to inhibit tumour cell proliferation or the comparative efficacy of AZ12253801 and the combined neutralising antibodies." (PMID 23826179, 2013). "In the reported case, it was determined that the tumor had very low expression of IGF1R, a plausible explanation for the lack of efficacy in this patient." (PMID 23730622, 2013). "For BC0145, the CSC frequency of IGF-1R+ cells was higher than IGF-1R- cells, which failed to generate any tumor with up to 105 cells (P = 0.0036)." (PMID 23663564, 2013). "No tumor exhibited activation of hepatocyte growth factor receptor (c-MET) or insulin-like growth factor 1 receptor (IGF-1R)." (PMID 24204737, 2013). "In human tumor cells co-expressing IGF-1R and IR, it was reported that co-targeting IGF-1R and IR with OSI-906 provides superior anti-tumor efficacy compared with targeting IGF-1R alone using a neutralizing antibody." (PMID 23525758, 2013). "Even though most of the studies on PAPPA so far suggested its tumor-promoting role is largely IGF-1-dependent, anti-PAPPA therapy might provide therapeutic effects beyond the inhibition of the IGF-1/IGF-1R signaling axis." (PMID 23896451, 2013). "Preclinical studies combining IGF-1R inhibition with imatinib, which among other things inhibits PDGFR, showed hints of activity that are encouraging in this usually highly chemotherapy-resistant tumor type." (PMID 23383402, 2013).
tumor (continued). "Inhibiting either IGF1R or EGFR results in activation of the reciprocal receptor, suggesting that combined inhibition of both pathways may yield enhanced tumor therapy." (PMID 24019942, 2013). "IGF-1R is overexpressed in most cancer cells, so it’s not surprising that some tumor suppressors exert anti-cancer activity through transcriptional suppression of IGF-1R gene." (PMID 23889969, 2013). "The insulin-like growth factor (IGF) signaling system plays a crucial role in human cancer and the IGF-1 receptor (IGF-1R) is an attractive drug target against which a variety of novel anti-tumor agents are being developed." (PMID 23525758, 2013). "MVP and IGF-1R expression were not differentially expressed according to tumour location and were not predictive factors in the whole series (Data not shown)." (PMID 22931894, 2012). "Indeed, a successful eradication of the tumor clone by PPP in the therapeutic setting of the 5TMM in vivo model set the stage for the use of inhibition of the IGF-1R in MM therapy." (PMID 22348393, 2012). "Also, both orthotopic and intratibial tumor growth of PC-3 cells were more potently inhibited by dual SFK and IGF-1R/IR blockade compared to either pathway alone, with a corresponding decrease in bone turnover markers." (PMID 23300537, 2012). "Tumours overexpressing MVP and IGF-1R were strongly related to poor disease-free survival (P = 0.008, Exp(B) = 2.730, CI95% (1.302-5.724)) and cause-specific survival (P = 0.014, Exp(B) = 2.570, CI95% (1.215-5.437)) in patients achieving tumour stages III-IV, in multivariate analysis." (PMID 22931894, 2012). "Alternative activation of c-Met and IGF1R abrogate the close association of EGFR with cell survival, accompanied by tumor growth that is independent of EGFR." (PMID 22815900, 2012). "Dual IGF-1R/IR and SFK inhibition may be a rational therapeutic approach in PCa by blocking both independent and complementary processes critical to tumor growth." (PMID 23300537, 2012). "In the light of this knowledge, it was perhaps not an unexpected finding that the mere presence of IGF-1 in serum, or the level of IGF-1R on the surface of tumor cells, has not been found to be a useful biomarker for tumor incidence or progression." (PMID 22348393, 2012). "One major mechanism of anti-tumor action induced by an anti-IGF-1R antibody, regardless of its being an agonist or antagonist, is to downregulate IGF-1R." (PMID 22952934, 2012). "Human prostate cancer cells usually form anchorage independent growth, however; when IGF-1R was abolished, these cells failed to grow in culture, and the same model showed no tumor formation in mice." (PMID 21729319, 2011). "This is the first long-term study of these treatment approaches in an autochthonous model of K-ras wild type intestinal tumourigenesis to examine tumour phenotypic change, adding significantly to the body of evidence supporting the importance of EGFR and IGF1R interactions." (PMID 21811251, 2011). "If this hypothesis is correct it may be possible to suppress or prevent tumour resistance to IGF1R blockade by inhibiting ERK activity; indeed we do see partial inhibition of ERK phosphorylation by adding gefitinib to IGF1R inhibition." (PMID 21811251, 2011). "In contrast, paired tissue analysis showed IGF1R levels in tumor tissues were similar to those in non-neoplastic samples." (PMID 20426842, 2010). "The majority of tumor samples expressed mRNA for EPOR, ERBB2, and IGF1R at varying levels." (PMID 21318160, 2010). "In current anti-IGF1R clinical trials, patient enrolment is not based on the expression of IGF1R in the primary tumour." (PMID 19491901, 2009). "Additionally, immunohistochemical (IHC) staining of total IGF-1R with an anti-total IGF-1R Ab (G11;Ventana) was performed on tissue microarrays (TMAs) containing 270 independent NSCLC tumor samples." (PMID 19806209, 2009).
tumor (continued). "These ‘direct-linkage AVE-1642 QDs’ bound to IGF1R-expressing cells in vitro, and they did not affect the nonspecific uptake or tumour targeting in vivo (data not shown)." (PMID 19491901, 2009). "In contrast, AVE-1642-conjugated Alexa 680 solely targeted to xenograft tumour and was able to detect IGF1R downregulation, with little nonspecific targeting to other tissues or organs in mice." (PMID 19491901, 2009). "Unlike HER-2, where expression levels are routinely measured by fluorescent in situ hybridisation or immunohistochemistry in clinical settings, a technique to quantitatively measure IGF1R level in tumour specimens has not yet been subjected to rigorous study." (PMID 19491901, 2009). "Indeed, ER+ tumours were scattered in subgroups 1 to 4 that are characterised by the over-expression of a cluster of genes, which includes CCND1, KRT19, IGF1R, LIV1, ESR1, GATA3, TFF1/pS2, ERBB4, PR and IGFBP4." (PMID 17338809, 2007). "On the other hand, IR-A dependent tumours would not be affected by a fully selective IGF-1R inhibitor." (PMID 15956962, 2005). "With the purpose to evaluate the specific contribution of IGF1R and IR in mediating ACC cell proliferation, we performed in vitro experiments with four different cell lines: H295R and JIL-2266, derived from ACC primary tumours, and MUC-1 and TVBF-7 derived from ACC metastatic tissues." (PMID 40038716, 2025). "Immunohistochemical staining was performed on a tissue microarray (TMA) comprising paired tumor and adjacent non-tumorous tissues from patients with iCCA, pCCA, and dCCA, which revealed significantly elevated IGF1R expression in tumor tissues across all subtypes." (PMID 41275311, 2025). "Tumor cells may develop drug resistance through various mechanisms, including overexpressing certain proteins (e.g., epidermal growth factor receptor/EGFR, insulin-like growth factor-1 receptor/IGF-1R, c-KIT), which can lead to inhibition of drug efficacy." (PMID 40584293, 2025). "Linsitinib-mediated IGF-1R inhibition was confirmed by immunoblot analysis of IGF-1R, AKT, and cleaved PARP in residual cancer cells, while apoptosis was quantified by flow cytometry of GFP-labeled cells; delayed tumor recurrence upon KRAS reactivation validated dormancy eradication in vivo." (PMID 41404065, 2025). "These failed trials may be due to therapy not being administered at the appropriate tumor stage, as our results demonstrate a narrow therapeutic window in which anti-IGF1R therapies are useful." (PMID 39075581, 2024). "Thus, activation of IGF1R signaling promotes EMP and tumor progression to a mesenchymal state." (PMID 39075581, 2024). "It has been reported that CuS NPs could enhance the ROS level in tumor cells by near-infrared laser irradiation, thus impeded bypass IGF1R and its downstream AKT/ERK/NF-κB signaling cascades to solve the resistance of gefitinib induced by IGF1R bypass." (PMID 39128942, 2024). "Given the complexity of the IGF-1R/IR family and the dynamic predominance of specific receptors and ligands in individual tumors, each class of anti-IGF/IGF-1R agents may offer unique advantages and different toxicity profiles in selected tumor settings." (PMID 39273251, 2024). "In addition, the IGF1/IGF1R pathway appears to be a key player in enhancing the immunosuppressive function of T-regs and impairing the recruitment of cytotoxic CD8+ T cells at the tumor site." (PMID 38420122, 2024). "The suppression of tumor growth by linsitinib (10 mg/kg) could not be attributed to the inhibition of the IGF1R on tumor cells, as linsitinib did not significantly add to the effect on tumor growth in Igf2-cKO mice." (PMID 39545420, 2024). "OSI-906 treatment did not reduce tumor growth, despite blocking IGF1R signaling." (PMID 39075581, 2024). "However, the involvement of IGF1R signaling in tumor-infiltrating immune cells at the TME is still not clear." (PMID 39450263, 2024).
tumor (continued). "Ligand binding triggers IGF-1R signaling via the PI3K/Akt and MEK/ERK pathways, as well as nuclear IGF-1R transport to activate gene transcription, thereby regulating resistance to apoptosis, cell proliferation, and cell cycle progression, as well as promoting tumor progression." (PMID 39770449, 2024). "They show anti-tumor activity against various targets such as EGFR, vascular endothelial growth factor (VEGF), PD-1, CTLA-4, receptor activator of nuclear factor-kappa B ligand (RANKL), insulin-like growth factor 1 receptor (IGF-1R), human epidermal growth factor receptor (HER2), cMET, and AXL." (PMID 38927911, 2024). "This suggests that the primary target of linsitinib may be the IGF1R pathway in fibroblasts rather than in tumor cells." (PMID 39545420, 2024). "In a different study, miR-133a-3p was shown to act as a tumor suppressor and to inhibit the proliferation, differentiation, and motility of cancer cells via different mechanisms, such as targeting several oncogenes, targeting the EGFR/Akt signaling pathway, and inhibiting IGF1R expression." (PMID 38793064, 2024). "Although such an effect was seen in up to 5–8% of target cells, the tumor-penetrating ability can be increased by retargeting AltMV SPV to an alternative receptor such as neuropeptide Y1, IGF-1R, or unknown surface proteins detected in our earlier investigation." (PMID 39459953, 2024). "Anti-tumor efficacy was not seen in NSCLC cells with mutations in those genes, indicating that EGFR and KRAS mutation status can be predictive markers of response to IGF-1R TKIs." (PMID 38540176, 2024). "Therefore, dual inhibitors targeting both IR and IGF-1R hold promise in inhibiting tumor progression effectively without impairing IR’s normal function." (PMID 37834454, 2023). "Low expression of miR-1294 can up-regulate the expression of downstream protein-coding genes microtubule nucleation factor (TPX2), IGF1R, MYC proto-oncogene, bHLH transcription factor (c-Myc) and TRL4, TRL6, TRL8, TRL9, enolase 1 (ENO1), thereby promoting the proliferation of various tumor cells." (PMID 37303740, 2023). "However, IGF1-mediated activation of IGF1R is blocked by SSTNIGF1R in the tumor cells, indicating that activation of IGF1R with or without IGF1 in the tumor cells is highly dependent on its linkage to Sdc1." (PMID 36968227, 2023). "Given the preponderance of data that links nuclear IGF-1R to worse outcomes after IGF-1R - directed treatments, inhibiting nuclear translocation of IGF-1R or inhibiting its sequestration in the nucleus could re-sensitize tumor cells to treatment." (PMID 37858153, 2023). "The elevated level of intracellular Ca2+ induces activation of the insulin-like growth factor 1 receptor (IGF-1R) via release of insulin-like growth factor 2 (IGF2) from airway epithelial cells, which leads to the transformation of the lung epithelial cells and to tumor initiation." (PMID 36835082, 2023). "IGF‐1R is upregulated in most malignant tumors, and its combination with the ligands IGF‐1 or IGF‐2 can activate the PI3K/AKT and Ras/Raf/MEK/ERK/MAPK signaling pathways, thereby promoting tumor proliferation, differentiation, and migration and playing a role in fine‐cell apoptosis inhibition." (PMID 36994237, 2023). "Their results suggest that IGF1 through IGF1R may be involved in early stages of tumour establishment, contributing to tumour cells anchorage by interaction with soluble and non-soluble factors produced by CAFs." (PMID 37033265, 2023). "Moreover, we found that NEDD4 promotes proliferation and tumor formation of GC cells sensitive to IGF1R inhibitor but not the insensitive ones in a PTEN-dependent manner." (PMID 36774408, 2023). "Moreover, it was discovered that CircGNB1 sponges miR-141-5p and upregulates insulin-like growth factor 1 receptor (IGF1R), which promotes proliferation and migration of TNBC cells, and increases tumor growth and the number of lung metastases in a mouse xenograft model." (PMID 37511619, 2023).